RNU6-873P (RNA, U6 small nuclear 873, pseudogene)
Gene: Small nuclear RNA gene on chromosome 3 (87,742,543 to 87,742,649, reverse strand). Ensembl gene ENSG00000200703.
Homologues: Orthologues: chimpanzee U6 (100% identical), pig U6 (88% identical), guinea pig U6 (86% identical), guinea pig U6 (83% identical). Paralogues in human: RNU6-1060P (88% identical), RNU6-15P (88% identical), RNU6-31P (88% identical), RNU6-45P (88% identical), RNU6-589P (88% identical), RNU6-1011P (87% identical), RNU6-10P (87% identical), RNU6-12P (87% identical), RNU6-13P (87% identical), RNU6-166P (87% identical), RNU6-224P (87% identical), RNU6-26P (87% identical), and 1288 more.